ADAMTS13 (ADAM metallopeptidase with thrombospondin type 1 motif 13)
Diseases named in the same sentence as ADAMTS13 in open-access papers (continued):
Sharing a sentence is not in itself a finding about the gene and the disease.
thrombotic thrombocytopenic purpura (continued). "Thrombotic thrombocytopenic purpura is a rare condition hallmarked by thrombotic microangiopathy (TMA) and dysfunctional ADAMTS13 enzymatic activity." (PMID 37465548, 2021). "Thrombotic thrombocytopenic purpura (TTP) is a serious and rare disease diagnosed by <10% activity of disintegrin and metalloprotease with thrombospondin type-I repeats-13 (ADAMTS13)." (PMID 31249968, 2018). "Acquired thrombotic thrombocytopenic purpura (TTP) is characterized by autoantibodies against a disintegrin and metalloproteinase with a thrombospondin type 1 motif, member 13 (ADAMTS13)." (PMID 28367342, 2017). "Thrombotic thrombocytopenic purpura (TTP) was excluded with a normal ADAMTS13 activity." (PMID 28343354, 2017). "In thrombotic thrombocytopenic purpura (TTP) or thrombotic microangiopathy (TMA), the enzyme activity of ADAMTS13 that cuts ultralarge von Willebrand multimers (UL-VWFM) is reduced." (PMID 27310951, 2016). "In the pathogenesis of thrombotic thrombocytopenic purpura (TTP), reductions in the enzyme activity of ADAMTS13, which cuts ultralarge von Willebrand multimers, generates shear stress on the microvascular endothelium, leading to platelet aggregation and the formation of a thrombus." (PMID 27310951, 2016). "Thrombotic thrombocytopenic Purpura (TTP) defined as ADAMTS-13 (A Disintegrin And Metalloprotease with ThromboSpondin type 1 domain 13) activity <10 % is a rare aetiology of thrombocytopenia during pregnancy, although the precise incidence is unknown." (PMID 26081109, 2015). "Thrombotic thrombocytopenic purpura (TTP) is a rare, life-threatening, thrombotic microangiopathy (TMA) characterized by severe deficiency in A Disintegrin And Metalloprotease with ThromboSpondin type 1 domain 13 (ADAMTS-13)." (PMID 26081109, 2015). "Thrombotic Thrombocytopenic Purpura (TTP) is an acute, life-threatening thrombotic microangiopathy caused by deficient activity of the von Willebrand factor (VWF) cleaving protease ADAMTS13 (a disintegrin and metalloprotease with thrombospondin type 1 motif, 13th member)." (PMID 25431165, 2014). "Currently, a severe deficiency in ADAMTS13 : AC, which results either from genetic mutations in the ADAMTS13 gene (Upshaw-Schulman syndrome, (USS)) or acquired autoantibodies against ADAMTS13, is thought to be a specific feature of thrombotic thrombocytopenic purpura (TTP)." (PMID 21994870, 2011). "Thrombotic thrombocytopenic purpura (TTP) is a life-threatening thrombotic disease characterized by a severe deficiency in the activity of a specific von Willebrand factor (VWF)-cleaving protease, a disintegrin-like metalloproteinase with thrombospondin type 1 motif 13 (ADAMTS-13)." (PMID 40821745, 2025). "Due to the unavailability of ADAMTS13 assays, risk scores like PLASMIC or French scores, which help distinguish thrombotic thrombocytopenic purpura (TTP), were not applied." (PMID 40772201, 2025). "In atypical hemolytic uremic syndrome (aHUS), cytokines are upregulated secondary to complement dysregulation, while in thrombotic thrombocytopenic purpura (TTP), inflammation may lower ADAMTS13 activity and potentiate thrombosis." (PMID 40901110, 2025). "We excluded thrombotic microangiopathy (including thrombotic thrombocytopenic purpura) as we did not observe any schistocytes in the peripheral blood, and von Willebrand factor-cleaving protease (ADAMTS13) activity was within the normal range." (PMID 39974298, 2025). "Running further investigations, such as Willebrand factor-cleaving protease, also known as ADAMTS13, that would allow distinguishing thrombotic thrombocytopenic purpura from other thrombotic microangiopathies, was not feasible at that point." (PMID 41536402, 2025). "Hereditary or primary acquired TMA syndromes like thrombotic thrombocytopenic purpura (TTP), which results from a severe deficiency of ADAMTS13, the most common cause of TMA among adults without cancer, should be excluded." (PMID 39997356, 2025).
thrombotic thrombocytopenic purpura (continued). "The study aims to examine the diagnostic potential, advantages, and weaknesses of the ADAMTS13 in thrombotic thrombocytopenic purpura (TTP) and present novel approaches to the diagnosis, treatment, and follow-up of TTP patients, which assimilates both clinical and laboratory data." (PMID 39125707, 2024). "Preservation of a disintegrin-like and metalloproteinase with thrombospondin type 1 motif 13 (ADAMTS13) activity coupled with a negative inhibitor excluded thrombotic thrombocytopenic purpura." (PMID 38255886, 2024). "Determining ADAMTS13 activity and Shiga toxin testing are crucial to rule out thrombotic thrombocytopenic purpura (TTP) and Shiga toxin E. coli HUS (STEC-HUS), respectively." (PMID 38105887, 2023). "None of the patients had thrombotic thrombocytopenic purpura (ADAMTS13 activity testing was measured in 6 patients (7.8%) and was always superior to 20%)." (PMID 37730583, 2023). "Thrombotic thrombocytopenic purpura (TTP) is a disease that develops when a disintegrin-like and metalloproteinase with thrombospondin type l motif 13 (ADAMTS13) activity decreases to < 10% of that in normal plasma, causing platelet thrombosis in microvessels throughout the body." (PMID 35979405, 2022). "Acquired thrombotic thrombocytopenic purpura (aTTP) was diagnosed in accordance with clinical manifestations along with initial blood test results and was confirmed later through findings of ADAMTS-13 low level activity and the ADAMTS-13 positive inhibitor." (PMID 35872667, 2022). "Thrombotic thrombocytopenic purpura (TTP) is one of two classic thrombotic microangiopathy (TMA) diseases induced by significantly reduced activity of metalloproteinase with thrombospondin type 1 motif, member 13 (ADAMTS13)." (PMID 35755834, 2022). "A stool culture and PCR for Shiga toxin-producing Escherichia coli was negative and thrombotic thrombocytopenic purpura was ruled out by normal ADAMTS13 activity and lack of an ADAMTS13 antibody." (PMID 33516177, 2021). "Thrombotic thrombocytopenic purpura (TTP), ADAMTS13, anemia." (PMID 37465548, 2021). "Normal ADAMTS13 activity in P34 does not support a diagnosis of AR Thrombotic thrombocytopenic purpura (MIM 274150), and therefore cannot explain hemolysis." (PMID 32641076, 2020). "Thus, in patients with low ADAMTS13 activity, platelets become more easily activated by the ultralarge VWF multimers, which can lead to a condition of thrombotic thrombocytopenic purpura (TTP)." (PMID 33490118, 2020). "Haemolytic uraemic syndrome (HUS) is a TMA characterized by predominant renal involvement and normal ADAMTS13 activity (> 10%), which excludes thrombotic thrombocytopenic purpura (TTP)." (PMID 31064333, 2019). "Thrombotic thrombocytopenic purpura (TTP) is a medical emergency and a form of thrombotic microangiopathy (TMA), in which the activity of the von Willebrand factor-cleaving protease, a disintegrin and metalloproteinase with thrombospondin type 1 motif, member 13 (ADAMTS13), is reduced." (PMID 31228952, 2019). "Thrombotic thrombocytopenic purpura (TTP) is a life-threatening form of thrombotic microangiopathy, characterized by microangiopathic hemolytic anemia (MAHA), thrombocytopenia, and neurological deficits, renal injury, and fever caused by the severe deficiency of plasma ADAMTS13 activity." (PMID 30834255, 2019). "Classical TMAs include thrombotic thrombocytopenic purpura (TTP) and Shiga toxin-induced hemolytic-uremic syndrome (HUS), in both of which activity of a disintegrin-like and metalloproteinase with thrombospondin type 1 motifs 13 (ADAMTS13) is reduced." (PMID 28856465, 2018). "Thrombotic thrombocytopenic purpura, first described as a clinical entity by Moschcowitz in 1924, is now etiologically defined by the lack of plasmatic ADAMTS13 activity." (PMID 28884355, 2018). "However, since its discovery in 2001, most ADAMTS13 research has focused on its interactions with VWF and its role in thrombotic thrombocytopenic purpura." (PMID 27787621, 2017).
thrombotic thrombocytopenic purpura (continued). "The importance of ADAMTS-13 is illustrated by the notion that absence of ADAMTS-13 is associated with platelet-rich microthrombi in the microvasculature, a disease known as thrombotic thrombocytopenic purpura (TTP)." (PMID 22563509, 2012). "A reduction or elimination of the protease activity of ADAMTS13 results in the VWF multimers remaining uncleaved in the circulating blood stream, which ultimately leads to intravascular thrombosis and an associated disorder known as Thrombotic Thrombocytopenic Purpura (TTP)." (PMID 19654870, 2009). "Furthermore, there is no consensus about the cutoff value of ADAMTS-13 to support a diagnosis of thrombotic thrombocytopenic purpura." (PMID 41001423, 2025). "The mainstay of therapy for thrombotic thrombocytopenic purpura (TTP) is urgent therapeutic plasma exchange (TPE), which removes autoantibodies and replenishes the ADAMTS13 enzyme." (PMID 41306494, 2025). "Delaying sample collection for ADAMTS13 activity testing from suspected patients with thrombotic thrombocytopenic purpura following administration of iodinated radiocontrast agents is not necessary, and recent contrast administration should not yield erroneous ADAMTS13 activity results." (PMID 39657035, 2025). "However, the common clinical presentation of TMAs, such as thrombotic thrombocytopenic purpura (TTP), in which ADAMTS13’s role is well understood, and PE/HELLP syndrome, suggests a linkage between the faulted expression of ADAMTS13 and the development of PE/HELLP syndrome." (PMID 38673014, 2024). "ADAMTS13 activity test to rule out thrombotic thrombocytopenic purpura was normal." (PMID 39717519, 2024). "In our case, ADAMTS13 activity and microbiological testing (BioFire GI panel) helped us to rule out the causes of TMA like thrombotic thrombocytopenic purpura (TTP), Shiga toxin-producing Escherichia coli-associated hemolytic uremic syndrome (STEC-HUS), and atypical HUS (aHUS)." (PMID 39717519, 2024). "Caplacizumab (ALX-0081) was recently approved by the FDA to treat thrombotic thrombocytopenic purpura (TTP), a disease characterized by the presence of active ultra-large VWF multimers due to insufficient ADAMTS13 activity." (PMID 33883551, 2021). "Thrombotic thrombocytopenic purpura (TTP) could not be ruled out until ADAMTS-13 results were available." (PMID 33413182, 2021). "The authors state “COVID-19 is associated with a substantial increase in von Willebrand factor levels, which can exceed the ADAMTS13 processing capacity resulting in the formation of large von Willebrand factor multimers indistinguishable from thrombotic thrombocytopenic purpura”." (PMID 34208470, 2021). "ADAMTS13, a metalloprotease that is able to cleave von Willebrand factor (VWF), was first discovered in thrombotic thrombocytopenic purpura (TTP)." (PMID 32075652, 2020). "However, the patient had a disintegrin-like and metalloproteinase with thrombospondin type 1 motifs, member 13 (ADAMTS13) levels of 41.7% (normal range 70–120%) and tested negative for ADAMTS13 inhibitors and thrombotic thrombocytopenic purpura." (PMID 28178155, 2017). "Thrombotic thrombocytopenic purpura (TTP) was suspected, and ADAMTS13 activity was measured; however, no significant decrease was observed (60%), and ADAMTS13 inhibitors were negative." (PMID 40092016, 2025). "At this point, ADAMTS13 (a disintegrin and metalloproteinase with thrombospondin type 1 motif, 13) for thrombotic thrombocytopenic purpura (TTP) had not been identified, and we wanted to further investigate the patient's down-trending Hgb." (PMID 40688966, 2025). "Thrombotic thrombocytopenic purpura (TTP) was ruled out with normal ADAMTS13 activity at 63% (reference range: > 60%)." (PMID 41220922, 2025). "Thrombotic thrombocytopenic purpura (TTP) could be a potential differential, especially given the presence of MAHA and thrombocytopenia; however, the normal ADAMTS13 level makes this less likely." (PMID 38826875, 2024).
thrombotic thrombocytopenic purpura (continued). "Thrombotic thrombocytopenic purpura (TTP) is brought on by a decline in or absence of the enzyme a disintegrin and metalloproteinase with thrombospondin type 1 motif, member 13 (ADAMTS13) activity." (PMID 37893544, 2023). "The patient was diagnosed with thrombotic thrombocytopenic purpura (TTP) prior to the genetic diagnosis, although ADAMTS13 activity was 38% and no inhibitory antibodies were found." (PMID 33712733, 2021). "In a non-cancer setting, the dysfunctional ADAMTS-13 in patients with thrombotic thrombocytopenic purpura (TTP), results in the presence of highly adhesive ultra-large VWF multimers in the blood that bind tightly to platelets to form aggregates." (PMID 33571850, 2021). "Activity of ADAMTS-13 (Von Willebrand factor-cleaving protease) was within the normal range (83 %), thus excluding thrombotic thrombocytopenic purpura (TTP)." (PMID 22890512, 2012). "Deficiency in the ADAMTS-13 function results in thrombotic thrombocytopenic purpura (TTP) but the ADAMTS-13 levels do not always correlate with the severity of TTP." (PMID 22178067, 2012). "At that point, the ADAMTS13 activity result had not yet been received, and thrombotic thrombocytopenic purpura (TTP) could not yet be excluded." (PMID 39917338, 2025). "The differential diagnosis initially considered thrombotic thrombocytopenic purpura (TTP) and other TMAs, but these were excluded based on preserved ADAMTS-13 activity (76%) and the absence of secondary triggers such as infection, autoimmune disease, or monoclonal gammopathy." (PMID 40422585, 2025). "Moreover, the negative results for Shiga toxin and the normal ADAMTS13 activity excluded other potential causes of hemolytic uremic syndrome (HUS), such as STEC infection and thrombotic thrombocytopenic purpura (TTP), respectively." (PMID 39371869, 2024). "ADAMTS13 (a disintegrin-like and metalloproteinase with thrombospondin type 1 motifs 13) activity did not decrease to 34%, and the diagnosis of thrombotic thrombocytopenic purpura (TTP) was negative." (PMID 35870879, 2022). "In the absence of ADAMTS13, spontaneous formation of VWF-platelet complexes leads to thrombotic complications as seen in patients with thrombotic thrombocytopenic purpura." (PMID 31921147, 2019). "For instance, several potentially relevant biomarkers such as ADAMTS13 and prealbumin (PAB) were not included in our dataset, and the associations with disseminated intravascular coagulation (DIC) or thrombotic thrombocytopenic purpura (TTP) were not analyzed due to the limited number of such cases." (PMID 41333802, 2025). "Importantly, inhibitory autoantibodies against the von Willebrand factor–cleaving protease (ADAMTS13 inhibitor) were negative in both cases, suggesting that the observed TMA was unlikely related to acquired thrombotic thrombocytopenic purpura (TTP) mediated by severe ADAMTS13 deficiency." (PMID 41516191, 2025). "The activity of A disintegrin and metalloproteinase with thrombospondin motifs 13 (ADAMTS13), a factor related to thrombotic thrombocytopenic purpura (TTP), was 78.52% (>10%, reference range: 42.16%–126.37%), and the patient tested negative for ADAMTS13 antibodies, ruling out TTP." (PMID 39144472, 2024). "For each of our patients, other confounding TMA syndromes, including Shiga toxin‐induced hemolytic uremic syndrome (HUS) and thrombotic thrombocytopenic purpura (TTP), were ruled out on the basis of negative Shiga toxin and normal ADAMTS13 activity, respectively." (PMID 35847716, 2020). "PE was initiated because thrombotic thrombocytopenic purpura (TTP) could not be ruled out initially, but was discontinued after the ADAMTS13 activity was determined to be 64 %." (PMID 27848226, 2017).
thrombotic thrombocytopenic purpura (continued). "vWF’s contribution to pro-thrombotic conditions is dramatically demonstrated by thrombotic thrombocytopenic purpura (TTP), a condition in which the ultra-large vWF multimers released by endothelial cells are not reduced in size by the circulating metalloprotease ADAMTS13." (PMID 27576551, 2016). "Determined by static assays, proteolytic activity <10IU/dL in patient plasma, in absence of ADAMTS13 autoantibodies, indicates Upshaw-Schulman syndrome (USS); the congenital form of Thrombotic Thrombocytopenic Purpura (TTP)." (PMID 32365113, 2020). "Workup for thrombotic thrombocytopenic purpura (TTP), HUS, heparin-induced thrombocytopenia was grossly negative on this admission, including ADAMTS13 activity (43%), C3 level (154 mg/dL), C4 level (41 mg/dL), negative heparin platelet antibody and a peripheral blood smear negative for schistocytes." (PMID 32481360, 2020).